IL6 (interleukin 6)
Diseases named in the same sentence as IL6 in open-access papers (continued):
Sharing a sentence is not in itself a finding about the gene and the disease.
tumor (continued). "In the present study, we expanded the application field of IL-6/IL-10 mRNA expression ratio into tumor tissues." (PMID 36371539, 2022). "IL-6 was reported to suppress the anti-tumor functions of T cells, which therefore impedes the effects of immunotherapy in patients." (PMID 36148946, 2022). "The results showed that either tumor volume or tumor weight was significantly decreased in mice treated with anti-PD-L1-masking EVs/IL6." (PMID 35692503, 2022). "Administration of tocilizumab also reduces IL-6-mediated tumor growth, breast CSCs, and the development of secondary metastases in a PTEN-/HER2+/trastuzumab-resistant xenograft mouse model." (PMID 35371975, 2022). "It has long been recognized that IL-6 promotes tumor growth and survival, with elevated levels of circulating IL-6 detected in patients with untreated mCRPC or CRPC, and serum levels correlated with shorter survival time." (PMID 35213227, 2022). "Most importantly, higher serum IL-6 levels are an independent predictor of a poor prognosis in GC; GC cells can secrete IL-6 and promote tumor growth, development, and migration." (PMID 35361764, 2022). "IL-6, a significant driver of hepatocellular carcinogenesis, is involved in tumor progression, metastasis and chemoresistance in HCC." (PMID 36071839, 2022). "Many cell types have been shown to produce IL-6 including monocytes, macrophages, T lymphocytes, endothelial cells, fibroblasts, and tumour cells." (PMID 35842694, 2022). "Combined blocking of IL-6 and PD-1/PD-L1 signals can eliminate their immunosuppressive effects in the tumor microenvironment." (PMID 35692583, 2022). "saw a synergistic increase in IL-6 production when activated T cells were co-cultured with CAFs derived from human NSCLC tumours." (PMID 35479076, 2022). "The molecules link between NF‐κB‐activated inflammation and tumour promotion has been proposed, such as IL‐1β, IL‐6 and TNF‐α, which are downstream targets of NF‐κB." (PMID 36124714, 2022). "The potential predictive value of baseline concentration of IL-6 in plasma and tumor tissues for PFS was confirmed with AUCs of 0.779 and 0.790, respectively." (PMID 35550592, 2022). "HSP72 and HSP105 in sEVs in the sera of melanoma, lung cancer and BC patients activate dendritic cells and trigger IL-6 production, which promote tumor invasion by increasing MMP9 expression." (PMID 36499561, 2022). "In the context of the host-tumor interface, increased IL-6 production by stromal cells and tumor-infiltrating immune cells (e.g., macrophages) has been implicated as part of the senescence-associated secretory phenotype (SASP)." (PMID 35406728, 2022). "In previous studies, the IL-6/JAK/STAT3 pathway in CRC promotes tumor genesis and tumor growth, as well as inhibits tumor cell apoptosis." (PMID 36551288, 2022). "We demonstrate that N6L remodels the PDAC tumour microenvironment, decreasing the frequency of immunosuppressive cells by targeting the tumour stroma and IL6 production by CAFs." (PMID 36077801, 2022). "Another study reported that IL6-prodicing TAMs confer chemoresistance on CRC tumor cells via the IL6R-STAT3 signaling pathway that inhibits expression of a tumor suppressor miR-204-5p." (PMID 36211375, 2022). "TNFα produces and maintains a network of other mediators that promote tumor growth and peritoneal spread by stimulating the release of IL-6 and other chemokines such as CCL2 and CXCL12, macrophage migration-inhibitory factor (MIF), and VEGF." (PMID 36142615, 2022). "The tumor-suppressive role of PTPN11 in HCC is mediated through the IκB kinase/NF-κB (IKK/NF-κB) pathway through promoting IL-6-stimulated Stat3 activation." (PMID 35057034, 2022). "In the tumor microenvironment, in addition to these factors, the interleukin 6 (IL-6) is an important pro-inflammatory cytokine, involved in the response of T helper 2 (Th2) cells." (PMID 35057010, 2022). "IL-6 is mainly responsible for cell cycle regulation, tumor angiogenesis, and local inflammation improvement." (PMID 35646915, 2022).
tumor (continued). "Levels of circulating IL-6 are elevated in cancer patients compared to adenoma patients or healthy subjects and correlate with larger tumor size, the occurrence of liver metastases, relapse, and reduced survival in CRC and colitis-associated cancers (CAC)." (PMID 35884974, 2022). "In particular, it is known that the relevant release of IL-6 and IL-8 by tumor cells has an autocrine effect, promoting tumor growth, angiogenesis, tumor cell motility, and the chemo-resistance phenomena, which correlate with poor prognosis in many cancers." (PMID 35337142, 2022). "Our previous work also showed that plasma IL-6 levels were positively correlated with postoperative tumor recurrence and tumor thrombus in microvessels." (PMID 35432524, 2022). "Other neuroendocrine mediators, such as interleukin 6 (IL-6) and matrix metalloproteinases (MMPs), are also secreted and play critical roles in the regulation of tumor growth and angiogenesis." (PMID 35223475, 2022). "Gemcitabine itself, as a stimulus, induces the iCCA interstitial reaction and increases the expression of IL-6, which enhance tumor cell gemcitabine resistance." (PMID 34975317, 2022). "Mast cells, through the release of IL-1, IL-4, and IL-6, are involved in the elimination of tumor cells and in the rejection of tumors." (PMID 36430483, 2022). "Meanwhile, IL-1A and IL-6 of Puget grade 2 tumor invasion to the hypothalamus were identified using LASSO regression." (PMID 36389809, 2022). "Over-activation of STAT3 in tumor cells also induces the production of IL-6, resulting in a positive feedback loop." (PMID 36591515, 2022). "IL-6 levels have been shown to correlate with tumor progression in a number of cancer types including oral and head and neck cancer." (PMID 36704239, 2022). "We subsequently analyzed the influence of the anatomical tumor localization on concentrations of CgA, the NETest, as well as IL-1β, IL-6, IL-8, IL-10, IL-18, and TNF." (PMID 36294509, 2022). "The effects of IL-6 can be direct on tumor cells, as well as indirectly through the promotion of angiogenesis and the modulation of stromal cells." (PMID 36172343, 2022). "In the follow up study, we expressed ZIL in combination with tumor antigen binders to generate bacteria with dual functionality that simultaneously target IL-6 and tumor antigens overexpressed on cancer cells." (PMID 35842694, 2022). "Hypoalbuminemia usually reflects insufficient oral intake and excessive tumor consumption that induces inflammatory cytokines such as IL-1, IL-6, and TNF-α." (PMID 36194563, 2022). "The protein level of IL-6 was analysed in the tumour and in the plasma of mice treated or not by N6L." (PMID 36077801, 2022). "In HCC, IL6 secreted by CAFs inhibits T-cell activity and induces immune tolerance by triggering the JAK-STAT3 pathway in tumor-associated neutrophils." (PMID 36032075, 2022). "More interestingly, the secretion of miR-21 and miR-29b by tumor cells has effect on immune cells and increases the production of IL-6." (PMID 35410210, 2022). "For example, tumor‐induced IL‐6 impairs the ketogenic response to reduced caloric intake, resulting in a systemic metabolic stress response that blocks anticancer immunotherapy." (PMID 36105371, 2022). "On the one hand, ample data accumulated over the last three decades to validate the involvement of IL-6 as an almost invariant presence at the host-tumor interface." (PMID 35406728, 2022). "Therapeutically, IL-6 inhibition diminished both tumor development and invasiveness by decreasing cell proliferation, EMT, DNA methyltransferase 1 expression, and angiogenesis." (PMID 36140470, 2022).
tumor (continued). "Using an in vitro complementation approach to model inter-clonal tumor cell interactions, we find that IL-6 secreted by HER2neg and IL-6 unresponsive IBC cells drives proliferation of HER2pos and IL-6R-expressing IBC cells." (PMID 35565421, 2022). "We previously demonstrated that tumor microenvironment interleukin-6/leukemia inhibitory factor (IL6/LIF) cytokines induce tumor cell JAK-STAT signaling to promote cancer growth." (PMID 36230597, 2022). "IL-6 in the tumor microenvironment promotes tumor formation by regulating all the hallmarks of cancer and many signaling pathways including metabolism, apoptosis, survival, proliferation, angiogenesis, invasiveness and metastasis." (PMID 35884907, 2022). "The elevated levels of IL-6 observed peaking at 5 days post treatment in this study are therefore consistent with an increase in tumor-antigen-specific T-cell response." (PMID 36532027, 2022). "M1-macrophages prompted the destruction of tumor cells, recruited tumor-killing leukocytes, and engulfed tumor cells by producing the immune-killing molecules such as ROS and nitrogen and inflammatory cytokines such as IL-6 and TNF-α." (PMID 35585567, 2022). "miR-155-5p in M2 macrophage-derived exosomes was found to be significantly associated with increased IL-6 expression, which was capable of mediating tumor immune escape through IL-6-related pathways." (PMID 36362044, 2022). "In this model, most mutations, including APC and KRAS, occur less often than in sporadic CRC and at later stages of tumor evolution, where they promote cytokine secretion, tumor growth, and angiogenesis via the NF-κB, IL-6/STAT3, or IL-23/Th17 pathways." (PMID 35884974, 2022). "We also measured the production of cytokines including interferon-β (IFNβ) and interleukin-6 (IL-6) in the plasma and tumor homogenates as PD markers." (PMID 36442099, 2022). "M2b/M1M2bM2c/M2b/M1M2bM2c is maintained in a cycle due to the action of a pro-inflammatory IL-1β.Like IL-6, IL-1β has two sides to a story: tumor promotion and tumor inhibition." (PMID 36544764, 2022). "Studies have indicated that IL-6 plays dual role both in promoting tumor growth and inducing adaptive immunity within the tumor microenvironment." (PMID 35300689, 2022). "Our results suggest that CM of activated RAW264.7 cells treated tumor possess higher CSCs (8.5%) compared to control (3.1%) and IL-6 neutralized CM treated tumors (6%)." (PMID 35300689, 2022). "In mouse tumor models, epinephrine induced selective mobilization of IL-6-sensitive NK cells while IL-6 inhibited the infiltration and activation of NK cells in TME." (PMID 36072337, 2022). "Chronic inflammation is closely related to tumor initiation and progression, and both interleukin-6 (IL-6) and tumor necrosis factor (TNF) are the important indicators of tumor-associated inflammation." (PMID 35889396, 2022). "Although an oversimplification, for charting purposes, the cytokines were split into three groups by their generalized tumor-destroying (IFN-γ, IL-2, and IL-5), tumor-promoting (IL-10 and IL-4), or SIRS-associated (IL-1β, IL-6, CXCL-1, and TNF-α) properties." (PMID 35465347, 2022). "The JAK2/STAT3 signaling pathway plays a key role in mediating multiple effects of IL-6 on tumor cell proliferation, anti-apoptotic, invasion and metastasis." (PMID 35790790, 2022). "One of the best-validated cytokines involved in tumor progression is the pro-inflammatory cytokine interleukin 6 (IL-6)." (PMID 36358310, 2022). "NLRP3, IL-1ß and downstream IL-6 are further activated following cancer therapies including doxorubicin, tumor cell-targeting CAR T cells and immune checkpoint inhibitors, contributing to the cytokine release syndrome and cardiac toxicity." (PMID 36466820, 2022). "Some cytokines, like interleukin‐1 (IL‐1), interleukin‐6 (IL‐6) and tumor necrosis factor‐alpha (TNF‐a), are secreted during hypoxia, which is a hallmark of tumor." (PMID 34196131, 2022).
tumor (continued). "The data showed that CM of activated macrophages enhanced tumor growth as compared to control whereas neutralization of IL-6 in CM of activated macrophages abrogated the effect." (PMID 35300689, 2022). "On top, an anti-IL-6R binding moiety that modulates the signalling of IL-6 released after T cell and macrophage activation is present to not only potentially support tumour eradication but also to mitigate CRS events." (PMID 36439165, 2022). "IL-17 can help tumor cells escape from host immunosurveillance and promote metastasis by stimulating the release of multiple cytokines, such as IL-6, IL-8, and G-CSFs." (PMID 35534547, 2022). "As a result, inflammatory cytokines are released from the inflammatory cells (TNF-α, IL-1β, IL-6, IL-8, etc.), promoting tumor invasion and progression." (PMID 35054779, 2022). "Upregulation of IL-4, IL-5, and IL-6 was detected in the healthy hemisphere in the first days after tumor resection, which later reverted to basal level, indicating a transient in-brain inflammatory response to the surgical intervention." (PMID 35884700, 2022). "High levels of IL6 were supposed to promote tumor development, and activation of the downstream pathway JAK/STAT3 was commonly associated with increased tumor burden." (PMID 35692503, 2022). "IL-6 is a cytokine produced in various inflammatory and immune-mediated conditions and was recently uncovered as a tumorigenic molecule in the tumor microenvironment." (PMID 36143043, 2022). "As with IL-6, elevated preoperative serum levels were found to be predictive of the malignant potential of the tumor in CRC patients." (PMID 36361914, 2022). "FIB is upregulated by the inflammatory cytokine, IL-6, and has been demonstrated to mediate cell proliferation and form an extracellular matrix that binds to tumor cell surfaces, further increasing cancer cell adhesion, invasion, and metastasis." (PMID 35774393, 2022). "Increased levels of IL-6 have been demonstrated in the immunohistochemistry of tumor tissues from DLBCL patients." (PMID 35163421, 2022). "Based on these data, we sought to investigate the functional role of an IL-6 blockade on the tumour microenvironment of mPDAC models." (PMID 36077801, 2022). "Prolonged exposure of tumor cells to Il-6 or IL-8 induced the appearance of senescent cells and together with the inflammatory milieu, reinforce the tumorigenic capabilities of the tumor cells and increasing tumor aggressiveness." (PMID 36564457, 2022). "In the metastatic setting, elevated pre-treatment CRP and IL-6 were independently associated with shorter PFS and OS, and provided useful information on prognosis in addition to the tumor mutational status (RAS and BRAF)." (PMID 36233472, 2022). "Muscle waste is driven partly by a procatabolic state invoked by proinflammatory cytokines, such as interleukin-6 and tumor necrosis factor, which are directly released by tumor cells or produced by the host’s immune response." (PMID 36352042, 2022). "In general, CAFs shape the tumor microenvironment by the production of proinflammatory cytokines, including IL-1β and IL-6, and express the ligands CXCL12, CXCL1, and G-CSF that can drive downstream immunosuppressive signaling pathways." (PMID 36010899, 2022). "The anti-inflammatory markers (IL-10, CCL18, and TGF-β) were upregulated, and the pro-inflammatory markers (TNF-α and IL-6) were downregulated by the macrophages that are differentiated within the tumor matrices." (PMID 36072957, 2022). "Some ILs as IL-1, IL-6, IL-8, IL-11, and IL-23 also promote an inflammatory microenvironment, and some of them are involved in tumor progression." (PMID 36226048, 2022). "IL-6 combined with IL-6R can activate anti-apoptotic pathways in tumor cells and prolong their survival." (PMID 35634292, 2022).
tumor (continued). "Of interest, MM cells secrete extracellular vesicles (EVs) that polarize recruited monocytes to an M2 phenotype with subsequent release of M2-associated cytokines such as IL6, IL10, IL8, and TNFα that promote tumor proliferation." (PMID 35954459, 2022). "Through paracrine signaling, TGF-β1 can help in the formation of the tumor microenvironment by activating CAFs to produce the extracellular matrix and IL-6." (PMID 35740372, 2022). "The proliferation of tumour cells and the development of cervical cancer were found to be stimulated by inflammatory cytokines such as IL-6, IL-8, and IL-1β." (PMID 36230832, 2022). "Asc administration decreases the levels of serum inflammatory cytokines IL-6 and IL-1β and concomitantly decreases tumor size." (PMID 36234722, 2022). "In line with the suppressive effect of STAT3 on NK-cell functionality reported in the murine system, tumor-derived cytokines, such as IL-6 and IL-8, impair human NK-cell function in a STAT3-dependent manner." (PMID 35865518, 2022). "Cytokine analysis can be used for VRL diagnosis; the amount of IL-10 derived from tumor cells can be measured and used to calculate the IL-10/IL-6 ratio." (PMID 36362676, 2022). "Further discussion will concentrate on the effects of IL-6 in the invasion-metastasis cascade across a range of cancer types, showing the applicability of targeting both IL-6 signalling and tumour cell migration as a therapeutic goal in cancer treatment." (PMID 36429126, 2022). "This study also demonstrated that CRC-induced TAMs promote tumor migration and invasion by its secreted IL6 that inhibits expression of a tumor suppressor miR-506-3p followed by production of CCL2 to further recruit TAMs." (PMID 36211375, 2022). "Previously, miR-26a was shown to suppress tumor growth and metastasis formation by targeting the IL-6/STAT3 pathway and modulate the neuroinflammatory response induced by TLR4 stimulation." (PMID 36499093, 2022). "It has been reported that interleukin-6 secreted by MSCs can increase the secretion of endothelin 1 by cancer cells, thereby enhancing tumor growth and angiogenesis, while other reports have reached the opposite conclusion." (PMID 35317758, 2022). "IL-17 induces a wide range of angiogenic mediators, including VEGF, IL-8 and IL-6, to promote tumor growth." (PMID 35493517, 2022). "The M2d subtype, which is mainly activated by tumor-related factors such as IL-6, promotes tumor growth and angiogenesis, which is the main component of TAMs and promotes tumor growth." (PMID 35326602, 2022). "Several factors, such as IL-6 and PTHrP, which are derived from tumor or immune cells, are involved in the regulation of UCP124,25." (PMID 35388147, 2022). "Neutrophils can secrete tumor promoting factors such as TGF-β, IL-6 and IL-8, creating a stimulatory environment for tumor growth." (PMID 35936670, 2022). "Targeting IL-6 as a therapeutic approach to overcome chemoresistance in tumor formation is critical, and HIF is required for cancer cell chemoresistance." (PMID 36550571, 2022). "WAT browning is an energy-releasing process that is accompanied by a rise in UCP1 expression that is commonly seen in CAC to meet tumor energy expenditure, which can be mobilized by cytokines, usually IL-6." (PMID 35740622, 2022). "Meanwhile, FO/Se treatment resulted in higher levels of plasma IFN-γ and IL-2 together with lower IL-6 in doxorubicin-treated tumor-bearing mice than does doxorubicin treatment alone." (PMID 36483592, 2022). "Under hypoxic conditions in an immunosuppressive TME, upregulation of IL-6R expression on tumour cells and increased IL-6 production have been reported, inducing M2-TAMs and further promoting tumour progression and expansion, and survival resistance." (PMID 36439165, 2022). "The interaction of the IL6 and TGFB1 signaling pathways plays an important role in SREs caused by tumor escape, bone colonization, and bone destruction." (PMID 35872837, 2022).